ALK (ALK receptor tyrosine kinase)
Diseases named in the same sentence as ALK in open-access papers (continued):
Sharing a sentence is not in itself a finding about the gene and the disease.
tumor (continued). "MYCN amplification is associated with poor prognosis in NB patients, and there is evidence to the effect that MYCN cooperates with ALK in a synergistic manner to promote tumor growth." (PMID 27049722, 2016). "Patients with epidermal growth factor receptor (EGFR) or anaplastic lymphoma kinase (ALK) genomic tumor aberrations should have disease progression on FDA-approved therapy for these aberrations prior to receiving pembrolizumab." (PMID 29152394, 2016). "Secondary resistances are acquired mechanisms after the tumor has been exposed to an ALK inhibitor and can be further classified into two categories: ALK dominant and ALK non-dominant." (PMID 26951079, 2016). "The assay is considered to be positive for ALK rearrangement if split pattern and/or single orange signal without corresponding green signal are identified in at least 15% of tumor cells, a cut off that was used in all crizotinib studies." (PMID 27769042, 2016). "The tumor sizes of the five patients were all ≤ 3 cm and significantly smaller than those of patients with either EGFR mutations or ALK fusions(P=0.017, P=0.011)." (PMID 27563816, 2016). "ALK FISH revealed 25% of tumor cells had red and green signals that were two or more signal diameters apart were observed." (PMID 26172300, 2015). "In phase 1 and 2 studies, crizotinib treatment resulted in objective tumor responses in approximately 60% of patients with ALK-positive NSCLC and in progression-free survival of 7 to 10 months." (PMID 25889062, 2015). "Of these 82 cases, four (5 %) demonstrated HCNGs of ALK (range 6–13 % of tumor cells) and include 1 ER−/PR−/HER2−, 2 ER+/PR−/HER2− and 1 HER2 only positive (ER−/PR−/HER2+) case." (PMID 26312204, 2015). "Unlike conventional IMT, EIMS is characterized by plump round-to-epithelioid tumor cells embedding in abundant myxoid stroma with inflammatory infiltrate, as well as immunopositivity for ALK, and frequent RANBP2-ALK fusion gene." (PMID 26178751, 2015). "These developed independently in subclones of the tumor cells and conferred marked resistance to two different ALK inhibitors." (PMID 25888090, 2015). "We have unravelled the functional consequences of the differential miRNA expression observed in ALCL ALK− versus ALCL ALK+ tumour cells." (PMID 25820993, 2015). "Therapeutic targeting of ALK rearrangement has led to a remarkable improvement of survival in ALK-rearranged NSCLC patients, and many studies are underway to reveal the oncogenic role of ALK in other tumor species." (PMID 25803816, 2015). "Tumours expressing full-length ALK, instead, rely on both ligand availability and adequate receptor density to promote homo-dimerization and stimulate activity at the cell surface." (PMID 26147305, 2015). "Growth of a tumor cell line derived from this EML4-ALK CRC patient was inhibited by ALK inhibitors crizotinib and entrectinib." (PMID 26172300, 2015). "We report the case of an ALCL patient whose tumor harbored the newly recognized TRAF1-ALK fusion and describe the clinical outcome after treatment with an ALK inhibitor." (PMID 26187744, 2015). "RT-PCR analysis performed in a panel of 6 RMS tumours (3 ARMSs and 3 ERMSs) confirmed that ALK and MET mRNAs are expressed at significantly higher levels in ARMS compared to ERMS." (PMID 26445453, 2015). "Noteworthy, the combination of X-396 plus TL[ALK-siRNA] significantly enhanced the anti-tumor activity of the single agents." (PMID 26299615, 2015). "Here, we synthesized peptides mimicking the proapoptotic domain of ALK and investigated their biological effects on tumor cells." (PMID 25950466, 2015). "In this paper, we propose miR-155 as a tumour driver in the majority of ALCL ALK− cases and demonstrate its functions in ALCL cell lines." (PMID 25820993, 2015). "The frequency of ALK rearrangement in CRC in this study was of 0.6% (1/172) among Korean CRC tumor samples." (PMID 26172300, 2015).
tumor (continued). "Taken together, our results indicate that the ALK-derived P36 peptide specifically induces apoptosis in ALK-expressing tumor cells." (PMID 25950466, 2015). "Although the inhibition of ALK activity by crizotinib treatment can reduce the stem-like properties of EML4-ALK+ tumor cells, but its efficacy is limited by variable primary response and acquired resistance." (PMID 26517679, 2015). "We show active regulation of interleukin production by miR-155 and that inhibition of miR-155 leads to reduced growth of ALCL ALK− tumours in murine engraftment models." (PMID 25820993, 2015). "ALK protein expression was observed in the cytoplasm of tumor cells with diffuse staining pattern in both differentiated and undifferentiated carcinoma areas with strong intensity." (PMID 26172300, 2015). "Preliminary clinical data have shown that X-396 is generally well-tolerated and has anti-tumor activity in patients with NSCLC bearing an ALK fusion protein." (PMID 26299615, 2015). "The overlapping detection of deregulated miRNAs in the different studies indicates that at least some of them most probably contribute to ALK mediated oncogenesis and/or tumor biology." (PMID 25688981, 2015). "RANBP2-ALK fusion likely plays the essential role in the carcinogenesis of this tumor, and ALK inhibitor is a promising treatment for this aggressive tumor regardless of its potential acquired resistance." (PMID 26178751, 2015). "ALK immunostaining was strongly present in the lesions, indicating that ALK overexpression is helpful for distinguishing IMT from malignant tumours in the urinary bladder." (PMID 25910080, 2015). "Consistently, ALK inhibition with crizotinib reversed the stem-like phenotypes of EML4-ALK+ tumor cells, suggesting ALK signaling is a central molecular axis in the stem-like phenotype of EML4-ALK+ tumor cells." (PMID 26517679, 2015). "Two secondary mutations, L1196M and C1156Y, within the kinase domain of EML4-ALK in tumor cells were reported in a patient during the relapse phase of treatment with an ALK inhibitor." (PMID 25888090, 2015). "Immunohistochemistry (IHC) and fluorescent in situ hybridization (FISH) revealed that the tumor had an ALK rearrangement." (PMID 25889062, 2015). "Epidermal growth factor receptor (EGFR) and anaplastic lymphoma kinase (ALK) are the most crucial tumor driver genes in NSCLC." (PMID 25676398, 2015). "The tumor cells were immunopositive to anaplastic lymphoma kinase (ALK) in smooth cytoplasmic pattern." (PMID 26178751, 2015). "The detection of an ALK rearrangement is currently performed on small biopsies or fine-needle aspirates of the tumor but is hindered by the very limited tissue quantities available." (PMID 25414829, 2014). "The first-line treatment for advanced non-small cell lung cancer (NSCLC) depends on the tumor histology and the presence of epidermal growth factor receptor (EGFR) mutation or anaplastic lymphoma kinase (ALK) rearrangements." (PMID 24748366, 2014). "Overall these results suggest that Myc cooperate with ALK-F1174L, as well as with ALK-R1275Q and ALK-wt, in enhancing the clonogenic capacities of tumor-derived cells in vitro and possibly tumor growth in vivo." (PMID 24947326, 2014). "We demonstrate here for the first time that ALK-wt expression in NCPC JoMa1 can drive malignant tumor formation in nude mice." (PMID 24947326, 2014). "In this case, the morphology of the neoplastic cell were different from ALCL, and the tumor cells were ALK- and EBER+." (PMID 25183396, 2014). "In contrast, ALK protein is only expressed in tumor tissue due to transcriptional activation from the promoter of the 5′-fusion partner to ALK but not in normal tissue and can be easily detected by immunohistochemistry (IHC)." (PMID 24744988, 2014). "So, our NCPC JoMa1 model revealed the strong tumor-initiating capacity of ALK-wt and activating mutants, in contrast to NB murine models." (PMID 24947326, 2014).
tumor (continued). "This was further corroborated with clinical analysis of tumor cells biopsied from patients resistant to ALK therapy." (PMID 25101240, 2014). "The role of ALK-wt, ALK-F1174L and ALK-R1245Q in NB tumor initiation was investigated in two NCPC models, MONC-1 and JoMa1." (PMID 24947326, 2014). "The authors concluded that crizotinib treatment resulted in tumor shrinkage in the majority of ALK-positive NSCLCs." (PMID 24955213, 2014). "LDK378 is an orally active ALK inhibitor which induced EML-ALK positive tumor regression in xenograft models and exhibited a minimally 70-fold greater ALK inhibition when compared to other kinases." (PMID 24955213, 2014). "Our data indicate that MassARRAY-based multiplex genetic testing both for somatic mutations and for ALK, ROS1, and RET fusion genes performed well with nucleic acid (DNA and RNA) extracted from FFPE tumor specimens obtained from patients with advanced NSCLC." (PMID 24810493, 2014). "In summary, we find that IHC and FISH techniques are optimal for the detection of ALK translocations in NSCLC patients if at least 50 tumor cells are scored and protocols are strictly followed." (PMID 25248157, 2014). "Similar to human pulmonary adenocarcinoma, significant increases in cpAC tumor mRNA expression and receptor phosphorylation of the anaplastic lymphoma kinase (ALK) tyrosine receptor were present when compared to the corresponding normal lung tissue." (PMID 24423144, 2014). "ALK protein expression can be observed in tumor cells with a predominantly cytoplasmic staining pattern only." (PMID 24667320, 2014). "We demonstrated that Myc upregulation was predominantly dependent on ALK activity, as treatments of tumor-derived JoMa1-ALK-expressing cells with TAE684 induced strong downregulation of Myc mRNA." (PMID 24947326, 2014). "Polysomy is common in ALK-rearranged lung cancer tumor thus, identifying all these criteria requires technical expertise and expert interpretation and is labor-intensive and time consuming." (PMID 24744988, 2014). "Once crizotinib was approved by the China Food and Drug Administration and the ALK gene translocation was identified in tumor cells by fluorescent in situ hybridization, the patient commenced treatment with crizotinib." (PMID 24885608, 2014). "For selected NSCLC groups according to gender, smoking status, tumor stage, or EGFR mutation, the incidence of ALK rearrangements ranged from 4.30% to 34.78% based on 20 articles (15 in East Asians; 3 in Caucasians; 2 in multi-ethnic groups)." (PMID 24959902, 2014). "The IHC showed that 53 (12.3%) patients were ALK-positive with a strong granular cytoplasmic staining in the tumor cells." (PMID 24992725, 2014). "We find that both IHC and FISH are reasonable approaches for primary routine ALK testing, provided that samples have at least 50 informative tumor cells." (PMID 25248157, 2014). "The anaplastic lymphoma kinase (ALK) gene, located on chromosome 2p23, is a receptor tyrosinase kinase protein and is capable of causing diverse tumor types of different lineages through a variety of molecular mechanisms." (PMID 25593912, 2014). "Rather, ALK+ ALCL tumour cells are heavily reliant on signalling pathways activated by ALK fusion proteins, and ALK+ status is a strong favourable prognostic indicator in ALCL." (PMID 25168906, 2014). "Preclinical studies show that tumors with aberrant activation of ALK tyrosine kinase are oncogene addicted to ALK intracellular signaling, and inhibition of the kinase by specific ALK targeting drugs results in tumor growth arrest and cell death." (PMID 25083769, 2014). "Despite the wide range in tumor involvement for all patients studied (0.01–80.0%), similar concordance was shown for all patients with known primary tumor ALK status." (PMID 25133137, 2014).
tumor (continued). "Collectively, these studies suggest that ALK and the ALKF1174L mutation contribute to tumor vasculogenesis and pericyte recruitment via the regulation of VEGF and MMP-9, leading to a dense vascular network with smaller, more stable vessels." (PMID 24667968, 2014). "We detected one ALK amplified (positive) case, with all the tumor cells in the TMA core displaying more than 6 ALK copy numbers/nucleus." (PMID 25188507, 2014). "Advanced-stage ALK-positive tumors have a relatively aggressive phenotype, which cannot be inferred from the size of the tumor alone." (PMID 24403104, 2014). "For this experiment, the NB1643M cell line expressing a homozygous ALK mutation was used, and Q/C analysis of the WGA products resulted in one or more bands for four of the six captured cells (two tumor and two WBCs)." (PMID 25133137, 2014). "NPM-ALK initiates a number of down-stream signalling events that ultimately promote the proliferation, survival, and migration of ALK+ ALCL tumour cells." (PMID 25168906, 2014). "ALK rearrangement was considered present when over 15% of the tumor cells displayed orange and green hybrid signals or an orange signal alone." (PMID 24938355, 2014). "Staging in the bone marrow is best achieved by using ALK staining to highlight the rare tumour cells." (PMID 24224107, 2013). "Global genomic comparison with SNP arrays showed tumours with ALK fusion to have fewer alterations in oncogenes and suppressor genes despite a similar overall aberration frequency, suggesting very strong oncogenic potency of ALK activation by gene fusion." (PMID 23289484, 2013). "The FC-IBC01 tumor emboli, which were encircled by lymphatic endothelium (red fluorescence), also expressed ALK protein (green fluorescence)." (PMID 24102046, 2013). "Our case demonstrates the utility of tumor re-biopsies in order to better understand the mechanisms of crizotinib resistance in patients with ALK-rearranged pulmonary adenocarcinoma." (PMID 24279718, 2013). "Preclinical studies have shown that treatment with ALK inhibitors can lead to drastic tumor regression in in vivo xenograft models." (PMID 23254764, 2013). "In most ALK-rearranged tumors, tumor nuclei were relatively monomorphic, except for 2 cases showing focal areas of pleomorphism." (PMID 23922677, 2013). "Stronger expression of phosphorylated ALK in BCC tumour nests than normal skin was observed by immunohistochemistry." (PMID 24163262, 2013). "Importantly, resistance-associated mutations in ALK have previously been found to co-exist with alternative pathway up-regulation, leaving open the possibility that this patient’s tumor cells had undergone additional changes that might have contributed to resistance." (PMID 24349229, 2013). "Although the tumor was thought to be removed completely, close followup is essential because the tumor was ALK positive, and recurrence in months to years after the surgery has been reported." (PMID 23936706, 2013). "It is now clear that genetic abnormalities of ALK and ALK signal pathway activation are present in numerous tumor types, with other ALK abnormalities still to be discovered." (PMID 24102046, 2013). "As for genomic loss, 9p21.3 (CDKN2A), 9p23-p24.1 (PTPRD) and 13q14.2 (RB1) were significantly less frequently deleted in ALK fusion-positive tumours." (PMID 23289484, 2013). "In some ALK-rearranged cases, tumor cells invaded the adjacent bronchiolar epithelium and showed the appearance of ‘budding off’ of small epithelial cell clusters into the lumen." (PMID 24194854, 2013). "FISH and IHC revealed that the original ALK rearrangement was still present, as we detected 60% of examined tumor cells with single-red ALK signal by FISH and intensely positive (3+) IHC-staining for ALK protein in the tumor tissue." (PMID 24279718, 2013). "The findings about specific antigens also suggest that ALK represents an ideal tumor antigen for vaccination-based therapies of ALCL and other ALK-positive tumors." (PMID 23840974, 2013).
tumor (continued). "We assessed ALK fusion status for 95 formalin-fixed paraffin-embedded tumor tissue specimens from 87 patients with NSCLC by FISH and real-time RT-PCR, for 57 specimens from 56 patients by targeted resequencing, and for 14 specimens from 14 patients by IHC." (PMID 23484153, 2013). "Activation of the anaplastic lymphoma kinase (ALK) receptor tyrosine kinase is a key oncogenic mechanism in a growing number of tumor types." (PMID 23889739, 2013). "That deletion of 9p23-24.1 and 13q14.2 including tumour suppressor genes was rare in ALK fusion-positive tumours suggests that they can grow even if the functions of these suppressor genes are retained." (PMID 23289484, 2013). "Three ALK-rearranged tumor cases showed morphology similar to IMA, including a predominant lepidic pattern of goblet cell proliferation with abundant extracellular mucin." (PMID 24194854, 2013). "A great advantage of immunohistochemistry is that tissue morphology is retained during analysis, and thus the detection of ALK fusions can be focused on the tumor areas." (PMID 23484153, 2013). "Reverse transcriptase-polymerase chain reaction (RT-PCR), fluorescence in Situ hybridization (FISH) and Immunohistochemical (IHC) stain were performed on tumor tissues of 312 NSCLC patients for detection of ALK rearrangements." (PMID 23951022, 2013). "PF-02341066 (crizotinib) is a novel dual c-Met and EML4-ALK inhibitor, and preclinical studies have shown that treatment with ALK inhibitors leads to drastic tumor regression in xenograft models." (PMID 23254764, 2013). "All of the 8 patients with high abundance of EML4-ALK positive cells in tumor tissues (assessed by the signal intensities of the RT-PCR product), were also have high expression of ALK protein (IHC3+), and positive for FISH, except one failed in FISH." (PMID 23951022, 2013). "There was positive nuclear staining of Ki67 and cytoplasmic staining of ALK within the same tumour nests." (PMID 24163262, 2013). "All of the 8 tumors with strong intensity of the PCR products (suggesting high abundance of EML4-ALK positive cells in tumor tissues) also had high expression of ALK protein by IHC stains and all positive for FISH tests, except one failed in FISH." (PMID 23951022, 2013). "In all ALK-positive cases, the tumor cell nuclei were relatively monomorphic, except for two cases showing focal areas of pleomorphism." (PMID 23922677, 2013). "20/25 IBC patient tumor samples had some type of ALK genetic aberrations including ALK copy numbers, ALK gene amplification and in the case of 1 IBC patient, EML4-ALK translocation." (PMID 24102046, 2013). "Recently, in newly developed preclinical models of IBC and patient tumor tissues, E-cadherin, anaplastic lymphoma kinase (ALK), and HSP90 have been identified as potential targets for IBC." (PMID 23401782, 2013). "FISH analysis of the specimen with dual-color break-apart rearrangement probe (Vysis LSI ALK; Abbott Molecular), detected ALK rearrangement in 40% of the analyzed tumor cell nuclei (100 tumor cell nuclei analyzed with a cut-off of 15%)." (PMID 24279718, 2013). "A possible predictive value of the copy number of the rearranged ALK gene in tumour cells and its influence on the level of ALK protein expression remains to be investigated." (PMID 22825000, 2012). "A number of clinical features and tumor phenotypes influence the disease outcome; the most important are age at diagnosis, tumor stage, amplification of the MYCN oncogene, activating ALK mutations, and somatic loss within chromosomal region 1p." (PMID 22984959, 2012). "PTN or ALK mRNA levels obtained from the tumor specimen were then separated into two groups, i.e., for those patients who were still alive 3 or 5 years after the initial diagnosis versus those patients who had perished by that time." (PMID 23267434, 2012).